LGALS9B (galectin 9B)
Description:
Binds galactosides.
Tractability: PROTAC: ubiquitination databases record sites on it.
Gene: Protein-coding gene on chromosome 17 (20,449,395 to 20,467,548, reverse strand). Ensembl gene ENSG00000170298.
Subcellular location (Human Protein Atlas): Cytosol
Gene Ontology:
Molecular function: protein binding; carbohydrate binding; galactoside binding; receptor ligand activity
Biological process: negative regulation of CD4-positive, alpha-beta T cell proliferation; negative regulation of type II interferon production; positive regulation of gene expression; negative regulation of alpha-beta T cell activation; positive regulation of immune response; positive regulation of mononuclear cell migration; regulation of innate immune response; regulation of T cell apoptotic process; regulation of T cell proliferation; signal transduction
Cellular component: cytosol; nucleus
Genetic constraint (gnomAD): Loss-of-function variants: 8 observed, 19.42 expected, observed/expected ratio (o/e) 0.41, 90% interval 0.24 to 0.74. The synonymous counts are far from expectation, so gnomAD's model fits this gene poorly and the ratio says little. Missense variants: 89 observed, 245.96 expected, observed/expected ratio (o/e) 0.36, 90% interval 0.3 to 0.43. Synonymous variants: 35 observed, 87.68 expected, observed/expected ratio (o/e) 0.4, 90% interval 0.3 to 0.53.
Homologues: Orthologues: dog LGALS9 (67% identical), Caenorhabditis elegans lec-12 (29% identical), Caenorhabditis elegans lec-3 (28% identical), Caenorhabditis elegans F40H6.5 (27% identical), Caenorhabditis elegans lec-1 (27% identical), Drosophila melanogaster galectin (26% identical), Drosophila melanogaster CG11374 (21% identical), Caenorhabditis elegans C27C7.5 (20% identical), zebrafish lgals3b (20% identical), Drosophila melanogaster CG13950 (17% identical), Caenorhabditis elegans lec-6 (15% identical), Caenorhabditis elegans F46A8.4 (14% identical), and 12 more. Paralogues in human: LGALS9C (99% identical), LGALS9 (95% identical), LGALS4 (36% identical), LGALS8 (31% identical), LGALS12 (27% identical), LGALS3 (22% identical), LGALSL (16% identical), LGALS7 (15% identical), LGALS7B (15% identical), LGALS1 (13% identical), GRIFIN (10% identical), LGALS2 (10% identical), and 4 more.
Diseases named in the same sentence as LGALS9B in open-access papers:
LGALS9B is named in the same sentence as 3 diseases in open-access papers, as found by Europe PMC text mining. Sharing a sentence is not in itself a finding about the gene and the disease. The quoted sentences say what the papers report.
tumor (3 papers, 2022 to 2023). "The functional role of LGALS9B remains unclear in KSHV pathogenesis, however, previous work found interactions between the galectin-1 (Gal-1) and specific target N-glycans link tumor hypoxia to neovascularization as part of the pathogenesis of KS." (PMID 36638143, 2023).
LGALS9B also shares sentences with these, for which no sentence is quoted: breast carcinoma (1 paper); breast tumor (1).